CDK1 (cyclin dependent kinase 1)
Diseases named in the same sentence as CDK1 in open-access papers (continued):
Sharing a sentence is not in itself a finding about the gene and the disease.
colorectal cancer (continued). "CDK1 was overexpressed in colorectal cancer and liver cancer and can promote cell proliferation and induce apoptosis." (PMID 35711939, 2022). "CDK1 has been reported to be overexpressed in a variety of malignancies, including pancreatic adenocarcinoma, hepatoma, colorectal carcinoma, and head and neck cancers, indicating that it plays a significant role in cell-cycle regulation and cancer formation." (PMID 36005140, 2022). "Sun W found the high ratio of nuclear and cytoplasmic expression of Cdk1 expression was meaningful to predict poor prognosis of colorectal cancer." (PMID 33758599, 2021). "Among all the CDKs, including CDK1, CDK2, CDK4, and CDK6, CDK4 was defined as an independent risk factor for colorectal cancer." (PMID 34595111, 2021). "In conclusion, we found that miR-378a-5p inhibited the proliferation of colorectal cancer cells, and CDK1 promoted the development of colorectal cancer." (PMID 33608020, 2021). "It has been reported that CDK1 is not only overexpressed in diffuse large B-cell lymphoma and melanoma but also highly expressed in colorectal cancer and prostate cancer." (PMID 34257537, 2021). "The results of this study help to elucidate the mechanism by which miR-378a-5p can be used as a tumor marker to inhibit the growth of colorectal cancer and CDK1, which is related to the prognosis of colorectal cancer patients." (PMID 33608020, 2021). "It is reported that CDK1 overexpression has been found in colorectal cancer, pancreatic ductal adenocarcinoma and thyroid cancer." (PMID 33767726, 2021). "This study established the therapeutic effectiveness of the treatment of BRAFV600E colorectal cancers based on the dual CDK1 and MEK inhibition mechanism." (PMID 34946546, 2021). "In this experiment, it was found that CDK1 is closely related to the development of colorectal cancer." (PMID 33608020, 2021). "Recent researches had revealed that the expression of CDK1 was high in different types of carcinomas, such as thyroid cancer, pancreatic ductal adenocarcinoma, colorectal cancer, and ovarian cancer and so on." (PMID 34187556, 2021). "A high CDK1 nuclear/cytoplasmic ratio was correlated with poor overall survival of colorectal cancer patients." (PMID 33014840, 2020). "Taken together, our data support development of novel strategies to inhibit CDK1 and/or GR for the treatment of metastatic human colorectal cancers." (PMID 31375708, 2019). "Medicine induces G2/M phase arrest in human colorectal cancer colon 205 cells through inhibition of CDK1 activity." (PMID 29190974, 2017). "CDK1 is overexpressed in many cancers, such as oral squamous cell carcinoma, esophageal adenocarcinoma, gastric cancer, liver cancer, colorectal cancer, ovarian cancer, and breast cancer." (PMID 28855742, 2017). "In particular, it has been reported that prognosis is poor in colorectal cancer patients with a high nuclear/cytoplasmic ratio of Cdk1." (PMID 27385216, 2016). "It has been reported that Cdk1 expression or activity is elevated in Hodgkin's lymphomas, human colorectal cancer, prostate cancer, gastric lymphoma, childhood acute lymphoblastic leukemia Therefore, Cdk1 is closely related with cancer progression." (PMID 27385216, 2016). "The results in this study were similar to those published by others to date, which showed higher CDK1 expression and activity in prostate cancer, colorectal cancer and epithelial ovarian cancer." (PMID 27835911, 2016). "Taken together, our results suggest that the CDK1 pTyr15 protein is a potential indicator of the progression of colorectal cancer." (PMID 27383761, 2016). "The results in this study were similar to those published to date, which show higher Cdk1 expression and activity in Hodgkin's lymphomas, colorectal cancer, prostate cancer, gastric lymphoma, and childhood acute lymphoblastic leukemia." (PMID 27385216, 2016).
colorectal cancer (continued). "The results of the evaluation of clinical samples suggested that CDK1 pTyr15 is a potential indicator of the disease-free survival probability for stage II colorectal cancer patients." (PMID 27383761, 2016). "These experiments confirmed that sites highly enriched in SOX9 binding overlap the NF-YA binding sites around the TSSs (within 500 bp of TSSs) of TOP2A, CCNB1, CCNB2 and CDK1 in colorectal cancer cells." (PMID 26040697, 2015). "This prompted us to investigate the role of Cdk1 in the clinical outcome of colorectal cancer patients." (PMID 25511643, 2014). "Recently, we found that cyclin-dependent kinase 1 (Cdk1) was overexpressed at the RNA level in circulating tumor cells of colorectal cancer when compared with control cells." (PMID 25511643, 2014). "Cyclin-dependent kinase pathways are considered possible targets for cancer treatment; however, the prognostic role of Cdk1 in colorectal cancer is still controversial." (PMID 25511643, 2014). "Cdk1 immunoreactivity was analyzed by immunohistochemistry (IHC) in 164 cancer specimens from primary colorectal cancer patients." (PMID 25511643, 2014). "The aim of the present study was to clarify the prognostic implications of Cdk1 expression in the nucleus and cytoplasm in colorectal cancer." (PMID 25511643, 2014). "Comparative analyses reveal both conserved and cancer-type-specific modules: the CDK1-centered cell-cycle network represents a conserved axis, whereas the PAK5-SRSF11-HSPA12A pathway in colorectal cancer and the CDK1-telomerase modules in HCC exemplify tissue-restricted mechanisms." (PMID 41584036, 2026). "Moreover, Cdk1-driven Sam68 cytoplasmic localization decreased apoptosis susceptibility and enhanced proliferation of HCT116 colorectal cancer cells." (PMID 37792222, 2024). "CDK1 has been reported to play a crucial role in the malignant progression and chemical resistance of multiple cancers, including human pancreatic ductal adenocarcinoma, ovarian cancer and colorectal cancer." (PMID 38967843, 2024). "In summary, ZNF880 may regulate CDK1 expression levels through transcriptional repression, thereby impacting the progression of colorectal cancer." (PMID 37370088, 2023). "Taken together, this study uncovers that DDX21 interacted with WDR5 to promote colorectal cancer cell proliferation by activating CDK1 expression, suggesting that targeting DDX21 may be an alternative new strategy for CRC treatment." (PMID 35371306, 2022). "Notably, high expression of the CDK1 gene can be a protective factor for DFS in colorectal cancer patients." (PMID 36090896, 2022). "It has been reported that CDK1 is a novel mediator of apoptosis resistance in BRAFV600E colorectal cancers whose dual targeting with a MEK inhibitor may be therapeutically effective." (PMID 35836300, 2022). "Notably, analysis from the Kaplan-Meier plotter dataset showed that high CDK1 expression was significantly associated with improved OS in blood cancers and improved DFS in colorectal cancers." (PMID 36090896, 2022). "In colorectal cancer cells, knock-down of CDK1 has induced sensitivity to apoptosis." (PMID 36266723, 2022). "Next, through TCGA database, immunohistochemical staining of pathological tissues, and cell function experiments, the role of the target gene CDK1 of miR-378a-5p was verified by database prediction, and dual luciferase reporter gene experiments in colorectal cancer cells were performed." (PMID 33608020, 2021). "Upregulation of CDK1 was observed in various cancers like human colorectal cancer, gastric lymphoma, Hodgkin’s lymphoma, prostate cancer, childhood acute lymphoblastic leukemia, and ovarian cancer; hence, CKD1 is associated with the prognosis of multiple malignant tumors." (PMID 34072728, 2021).
colorectal cancer (continued). "To further investigate the molecular mechanism of HIF-1α destabilization by CDK1 or CDK4/6 inhibitors, we performed a proteomic screen on immunoprecipitated HIF-1α from hypoxic colorectal cancer cells that were either untreated or treated with CDK1 inhibitor Ro3306 and CDK4/6 inhibitor palbociclib." (PMID 34611473, 2021). "Recent findings show that CDK1 affects 5-Fu resistance in colorectal cancer." (PMID 34603487, 2021). "The role of miR-378a-5p and CDK1 in colorectal cancer (CRC) was investigated in this study." (PMID 33608020, 2021). "Interestingly, it has been recently proposed that CDK1 is responsible for apoptosis resistance in BRAFV600E colorectal cancer; indeed, the combination of a CDK1 inhibitor with a MEK/ERK inhibitor enhanced apoptosis." (PMID 32948832, 2021). "A study was conducted to determine whether the CDK1 antagonist enhances the efficacy of MEK inhibition in BRAFV600E colorectal cancer cells." (PMID 34946546, 2021). "In our view, the altered ubiquitination of CDK1 may explain its increased protein level and abnormal subcellular localization in human colorectal cancer." (PMID 33014840, 2020). "Moreover, the protein expression level of CDK1 in 7 out of 12 patients with colorectal cancer was high." (PMID 33014840, 2020). "CDK1 expression and activity are elevated in colorectal cancer, prostate cancer, and lymphomas." (PMID 30765611, 2019). "Correlation between CDK1 pTyr15 expression and clinicopathological features in colorectal cancer." (PMID 27383761, 2016). "We suggest that Cdk1 N/C expression ratio determined by IHC staining could be an independent prognostic marker for colorectal cancer." (PMID 25511643, 2014). "Therefore, we attempted to determine the impact of Cdk1 on the clinical outcome of colorectal cancer patients to further identify its role in colorectal cancer." (PMID 25511643, 2014). "This is evidence that the Cdk1 N/C expression ratio could be an independent prognostic marker for colorectal cancer." (PMID 25511643, 2014). "14-3-3 σ, an isoform not expressed in lymphocytes, binds Cdk1 during G2,M arrest caused by adriamycin in the colorectal cancer cell line HCT116, and thus there is precedent for such an interaction." (PMID 18445273, 2008). "For instance, in colorectal carcinoma (CRC) with the BRAF V600E mutation (8% of CRC cases), treatment with CDK1 inhibitors significantly enhances the therapeutic efficacy of MEK inhibitors by reactivating caspase 8 activity." (PMID 39800748, 2025). "Therefore, inhibition of SRC activity and/or activation of CDK1 could sensitize human colorectal cancer cells to VU‐0365114." (PMID 37842807, 2024). "Finally, the protein expression level of CDK1 is generally high in colorectal cancer." (PMID 33014840, 2020). "However, Cdk1 N/C expression ratio determined by IHC staining could be an independent prognostic marker for colorectal cancer." (PMID 25511643, 2014). "KIF18A knockdown increased the protein expression of p21, and reduced the protein expression of CDK1 and cyclin B1 in NCI-H747, SW620 and CT26 CIN+ colorectal cancer cells, suggesting that KIF18A inhibition triggered G2/M phase arrest." (PMID 40175357, 2025). "For example, in human colorectal cancer (CRC) cells, DDX21 binds to the CDK1 promoter, interacting with WDR5 to enhance H3K4me3, which activates CDK1 expression and supports cell proliferation." (PMID 39769343, 2024).
colorectal cancer (continued). "In colorectal cancer, SNHG4 promoted the cellular proliferation via accelerating cell cycle through regulating miR‐590‐3p/CDK1 axis." (PMID 36565037, 2023). "On the other hand, in colorectal cancer HCT116 cells, C6 inhibited the activation of ERK1/2, cyclin-dependent kinase 1, and AKT, down-regulated the protein level of XIAP, and up-regulated pro-apoptotic Bax and caspase-3/7 expression." (PMID 35408786, 2022). "The universal effect of HIF1α inhibition by combination of CDK1 knockdown and HSP90 inhibition among various colorectal cancer cell lines prompted us to investigate the therapeutic potential of such combination strategy." (PMID 34686682, 2021). "For example, in pancreatic ductal adenocarcinoma, overexpression of CDK1 indicates poor prognosis, and CCNA2 is considered a possible biomarker for progression (eg, growth and apoptosis) of colorectal cancer." (PMID 33428596, 2021). "In our present studies, dual targeting of CDK1 or CDK4/6 and HSP90 robustly reduced the level of HIF1α and synergistically inhibited cell viability in colorectal cancer lines." (PMID 34686682, 2021). "For example, synergistic effects of CDK1 inhibitors and MEK/ERK inhibitors can promote the apoptosis of colorectal cancer cells." (PMID 34585634, 2021). "In both HeLa and human colorectal cancer (HCT 116) cells, SBI‐0206965 decreased the level of cyclin B1 that forms an active complex with CDK1 to initiate mitotic entry." (PMID 33040463, 2020). "For instance, ZFAS1 is significantly up-regulated in colorectal cancer tissue, and ZFAS1 silencing decreases tumor proliferation with G1-arrest via interacting with cyclin-dependent kinase 1 (CDK1)." (PMID 29262629, 2017). "Similarly, AM-1882 treatment promoted the protein expression of p21, and suppressed the protein expression of CDK1 and cyclin B1 in NCI-H747, SW620 and CT26 CIN+ colorectal cancer cells." (PMID 40175357, 2025). "In colorectal cancer, CTD inhibited cyclin-dependent kinase 1 (CDK1) and promoted apoptosis, while also suppressing the migration and invasion of gastric cancer cells by inhibiting the PI3K/Akt signaling pathway via colon cancer-associated transcript 1 (CCAT1)." (PMID 41339928, 2025). "There are also reports on the overexpression and oncogenic functions of DPP3 related to poor survival in numerous other malignancies, including colorectal cancer, where DPP3 was found to target cyclin-dependent kinase 1 (CDK1), multiple myeloma, and esophageal carcinoma." (PMID 39941813, 2025). "More intriguingly, the stabilization of pVHL by targeting CDK1 could also be a common regulatory mechanism in various types of cancer cells harboring wild-type VHL, including TNBC, pancreatic cancer, colorectal cancer and ovarian cancer." (PMID 36813923, 2023). "Recent studies have found that CDK1 activates JAK–STAT3 signaling in lung and colorectal cancer." (PMID 37743465, 2023). "Other than that, knockdown of RPS9 induced G2/M arrest of colon cancer cells by downregulating CDK1 expression at the promoter level and dysregulation of RPS9 may be involved in microsatellite instability of colorectal cancer 31] [32." (PMID 35281852, 2022). "There were no reports on the effect of CDK1 on survival progression in blood cancer, colorectal cancer, and esophageal squamous cell carcinoma." (PMID 36090896, 2022). "In colorectal cancer, lncRNA ZFAS1 may function as an oncogene by modulating ZEB1 to induce the expression of EMT, or combing with CDK1 and sponging with miR-590-3p to inhibit apoptosis." (PMID 28977885, 2017). "CDK1, HMGB2, SSRP1, and H2AFV may serve as key nodes for HMGB1 in colorectal cancer." (PMID 36230798, 2022). "Moreover, studies have shown that the overexpression of CDK1 in colorectal cancer, and the authors found that the decreased proliferation of colorectal cancer cells after NFE2L3 knockout may be due to the decreased CDK1 activity." (PMID 34586751, 2021).
colorectal cancer (continued). "In addition, CDK1, HMGB2, SSRP1, and H2AFV may serve as key nodes for HMGB1 in colorectal cancer." (PMID 36230798, 2022). "In contrast, silencing KIF18A showed no apparently influence on protein expression of p21, CDK1 and cyclin B1 in HCT-116 and MC38 CIN- colorectal cancer cells." (PMID 40175357, 2025).
hepatocellular carcinoma (105 papers, 2011 to 2026). A malignant tumor that arises from hepatocytes. "TCTP and CKS2 expression patterns are linked through the TCTP/CDC25C/CDK1 pathway, which was shown to be dysregulated in hepatocellular carcinoma." (PMID 40809150, 2024). "High CCNB1, CCNB2, and CDK1 expression has been associated with inferior prognosis in hepatocellular carcinoma patients." (PMID 38102624, 2023). "Previous studies have shown that high CDK1 expression is significantly associated with reduced overall survival in patients with colon cancer and hepatocellular carcinoma." (PMID 36090896, 2022). "Previous studies have demonstrated that the expression of CDK1 is increased in some human tumors, and an increase in CDK1 expression is associated with a poor prognosis for hepatocellular carcinoma and pancreatic ductal adenocarcinoma." (PMID 35681641, 2022). "Commonly, the high expression of CDK1 is associated with over-proliferation and can be a prognostic factor in many cancers, including epithelial ovarian cancer, hepatocellular carcinoma, non-Hodgkin's lymphomas and prostate cancer." (PMID 29069733, 2017). "Moreover, high expression of CDK1 in subtype 5 is closely associated with the development of many cancers, including hepatocellular carcinoma." (PMID 39944086, 2025). "Furthermore, CDK1 was frequently overexpressed in hepatocellular carcinoma and associated with tumor progression." (PMID 34023852, 2021). "Some researchers have found that CDK1 and cyclin B1 may be potential diagnostic biomarkers for rhabdomyosarcoma and hepatocellular carcinoma." (PMID 33608020, 2021). "It is closely related to cyclin CDK1, which could cause G2/M phase arrest in prostate cancer cells and is known to play an important role in the occurrence and development of hepatocellular carcinoma." (PMID 31505835, 2019). "This study provides comprehensive computational evidence that berberine exerts anti-hepatocellular carcinoma effects through dual targeting of AURKA and CDK1, two critical cell cycle regulators frequently overexpressed in hepatocellular carcinoma." (PMID 41226349, 2025). "CDK1 is involved in cell cycle regulation (G2-M transition and regulator of G1 progression and G1-S transition), which is overexpressed in hepatocellular carcinoma (HCC) and CRC tissues." (PMID 39949372, 2025). "The use of bioinformatics to study CDK1 as a therapeutic target for liver fibrosis and hepatocellular carcinoma has important potential, but there are many limitations." (PMID 40332418, 2025). "Through bioinformatics and related statistical methods, we visually demonstrate the different effects of immunosuppressants and immunostimulants on CDK1 and its methylated forms in hepatocellular carcinoma (HCC)." (PMID 40332418, 2025). "CDK1, as a key enzyme in cell cycle regulation, shows promising applications in the treatment of liver fibrosis and hepatocellular carcinoma." (PMID 40332418, 2025). "ASRGL1 strongly inhibits the development of hepatocellular carcinoma by inhibiting the formation of the cyclin B/CDK1 complex, ultimately leading to the failure of transition from the G2 to M phase of the cell cycle." (PMID 39883700, 2025). "Numerous studies have reported that CDK1 is abnormally expressed in various tumors, such as melanoma, hepatocellular carcinoma, and pancreatic ductal adenocarcinoma, and is related to the degree of tumor malignancy." (PMID 35251377, 2022). "Actually, CDK1 was also found to be a downstream effector in the DEPDC1B-related regulation of hepatocellular carcinoma." (PMID 36568241, 2022). "Accordingly, analysis of hepatocellular carcinoma cells revealed that negative regulation of cyclin B and CDK1 led to cell cycle arrest in the G2/M phase." (PMID 35267423, 2022). "Metformin can arrest cells in G2/M phase by reducing the expression of CDK1 and ultimately inhibiting the proliferation of hepatoma cells." (PMID 35836300, 2022).